NEK4 (NIMA related kinase 4)
Diseases named in the same sentence as NEK4 in open-access papers (continued):
Sharing a sentence is not in itself a finding about the gene and the disease.
cancer (14 papers, 2016 to 2025). A tumor composed of atypical neoplastic, often pleomorphic cells that invade other tissues. "Examining gene and pathway alterations in a NEK4-deficient background can reveal novel targets for developing targeted cancer therapeutics." (PMID 41001016, 2025). "Although NEK4 has been reported to play some roles in DNA repair and apoptosis, little is known about its effect on cancer cell EMT, which is closely associated with the potential of cancer cell invasion and metastasis." (PMID 30247800, 2018). "Since Survivin is known to prevent apoptosis by inhibiting caspase activation, NEK4 inhibition may render cancer cells more susceptible to therapies like TRAIL that induce apoptosis." (PMID 41154634, 2025). "Suppression of NEK4 could cause defects in DNA repair and sensitize cancer cells to apoptosis." (PMID 35721059, 2022). "The evolving picture of NEK4 in cancer biology emphasizes its potential not only as a single therapeutic target but as an essential molecule in cell cycle regulation." (PMID 41154634, 2025). "NEK4 depletion induces a decrease in cell viability in different cancer cell lines as evidenced by our and others’ results." (PMID 41001016, 2025). "We employed siRNA-mediated knockdown of NEK4 in different cancer cell lines and evaluated cellular proliferation via live-cell imaging." (PMID 41001016, 2025). "In the process of cancer development, NEK4 can repair defects by inhibiting DNA, which makes cancer cells sensitive to apoptosis." (PMID 35105934, 2022). "We confirmed the expression of NEK4 in our PC9 cell line model based on the publicly RNA-seq data available through the Cancer Cell Line Encyclopedia (CCLE)." (PMID 33435251, 2021). "NEK4 appeared to be also connected to tumor necrosis factor-related apoptosis-inducing ligand (TRAIL) resistant cancer cells." (PMID 32294979, 2020). "Down-regulation of NEK4 expression also notably enhanced cancer cell death after TRAIL treatment in 3D model systems." (PMID 27602754, 2016). "Quercetin inhibits protein kinases involved in deregulated cell growth in cancer cells, and NEK4 is a known target of quercetin." (PMID 27602754, 2016). "In contrast, over expression of NEK4 suppressed TRAIL-induced cell death in TRAIL-sensitive cancer cells." (PMID 27602754, 2016). "Taken together, these results suggest that downregulation of NEK4 sensitizes TRAIL-exposed cancer cells to apoptosis." (PMID 27602754, 2016). "In this study we found that knock down of NEK4 accelerated the sensitization of cancer cells to TRAIL both in vitro and in vivo, whereas ectopic expression of NEK4 blocked cell death." (PMID 27602754, 2016). "We envision future NEK4 inhibitors to be used in combination with DNA-damaging agents to enhance toxicity to cancer cells for improving patient outcomes, but further exploring why some cancers’ growth is potentiated by NEK4 knockdown is critical for proper patient stratification." (PMID 41001016, 2025). "NEK4 may therefore play a critical role in diseases arising due to cilium dysfunction and ciliopathies, including certain types of cancers." (PMID 41001016, 2025). "Interestingly, recent studies also point toward NEK4 involvement in critical processes that drive cancer progression, such as the epithelial–mesenchymal transition (EMT), mitochondrial dynamics, and the sensitivity of cancer cells to chemotherapy." (PMID 41154634, 2025). "On a protein level, interaction of HYAL4 with NEK4 may play an important part in the epithelial-to-mesenchymal transition of cells during the development of cancer." (PMID 34746156, 2021). "In this context, two more studies relating NEK4 to cancer development were published." (PMID 32294979, 2020).
cancer (continued). "Moreover, investigation is also required to assess the relationship between NEK4 and survivin expression in various types of cancers, using a large number of samples." (PMID 27602754, 2016). "Knockdown of NEK4 induced cell death in TRAIL-resistant cancer cells." (PMID 27602754, 2016). "Knockdown of NEK4 sensitized TRAIL-resistant cancer cells and in vivo xenografts to cell death." (PMID 27602754, 2016). "We and others have suggested that NEK4 may be an attractive target for multiple cancer types." (PMID 41001016, 2025). "Given its possible cellular functions, NEK4 may also be involved in cancer progression." (PMID 32294979, 2020). "For example, during cancer metastasis, NEK5 activity is coordinated with that of other NEK family members, such as NEK4 and NEK6, to orchestrate microtubule organization." (PMID 41154634, 2025). "NEK4 is present in most primary carcinomas where it acts as a positive regulator for EMT, resulting in an increased potential for cancer cell migration and invasion." (PMID 34746156, 2021). "It was recently reported that quercetin inhibits a panel of kinases including NEK4, NEK9, and ABL1 in cancer cells." (PMID 27602754, 2016). "There are limited publications about the function and roles of NEK3, NEK4, and NEK5 in cancer." (PMID 37835513, 2023). "For instance, inhibiting NEK4 could be beneficial in preventing metastasis by blocking EMT; however, the same action could induce resistance to taxane-based chemotherapies, which are a cornerstone of treatment for many cancers." (PMID 41154634, 2025).
tumor (11 papers, 2016 to 2026). "Clinically, NEK4 mutations were significantly associated with tumor site (P=0.02), NEK9 with tobacco exposure (P=0.01), and NEK10 with improved overall survival (P=0.01)." (PMID 41716219, 2026). "Meanwhile, EMT and its intermediate state play important roles in tumor invasion and metastasis; hence, NEK4 knockout can reduce the metastasis rate of lung cancer cells." (PMID 35105934, 2022). "In contrast, downregulation of NEK4 sensitizes tumor cells to TRIAL-induced apoptosis via decreased levels of survivin, an anti-apoptotic protein." (PMID 33435251, 2021). "IHC results confirmed a decreased expression of NEK4 in the tumor of A549‐shNEK4 group, and this verified the knockdown effects of shNEK4." (PMID 30247800, 2018). "The colony number of the pulmonary tumors formed in the mice with A549‐shNEK4 cells injection was markedly lower than that in the mice with A549‐shcon cells, indicating that NEK4 contributed to tumor invasion and metastasis." (PMID 30247800, 2018). "Using a mouse model with tail vein injection of NEK4 knockdown stable cell line, we found a lower rate of tumor formation and metastasis of the NEK4‐knockdown cells in vivo." (PMID 30247800, 2018). "Utilizing biomimetic carriers such as leukosomes for microRNA-based gene therapy could provide a platform to modulate NEK4 or its downstream pathways, especially as these preferentially hone to areas of inflammation, such as what may be found in a tumor." (PMID 41001016, 2025). "Hence, these results indicated that the knockdown of NEK4 increased the expression of E‐cadherin and inhibited the tumor formation in the mice pulmonary." (PMID 30247800, 2018). "We next examined the expression of NEK4 and survivin in tumor tissues." (PMID 27602754, 2016). "For testing in vivo function of NEK4, we established a pulmonary metastasis mouse model with the tail vein injection of A549‐shNEK4 or A549‐shcon cells to investigate whether the knockdown of NEK4 impacted tumor invasion and metastasis in vivo." (PMID 30247800, 2018). "In this study, NEK4/6/8 was highly expressed in LUAD, which was closely related to tumor stage and nodal metastasis status." (PMID 35105934, 2022). "Additionally, according to the UALCAN database, the mRNA expression levels of NEK2, NEK3, NEK4, NEK5, NEK6, and NEK8 were significantly positively correlated with the tumour grade, whereas that of NEK10 was inversely associated with this factor." (PMID 38706902, 2024). "Because the inhibition of NEK4 sensitize cells to TRAIL-mediated cell death in vitro, we further examined whether the depletion of NEK4 enhance the anti-tumor activity of TRAIL in vivo." (PMID 27602754, 2016).
psychiatric disorder (2 papers, 2024 to 2025). A disorder characterized by behavioral and/or psychological abnormalities, often accompanied by physical symptoms. "A Mendelian randomization study identified a total of 31 promising drug targets for psychiatric disorders, with NEK4 being one of the significant genes specifically associated with SCZ." (PMID 39734669, 2024). "Notably, NEK4 is involved in processes related to ciliary structure and function, which are linked to neuronal signal transduction and psychiatric disorders." (PMID 39950180, 2025).
neurological disorders (1 paper, 2025). "In addition to its attractiveness as a target for multiple carcinomas, NEK4 has also been identified as a potential drug target in neurological disorders." (PMID 41001016, 2025).
NEK4 also shares sentences with these, for which no sentence is quoted: ovarian carcinoma (4 papers); autoimmune encephalitis (1); brain disorder (1); cervical cancer (1); clear cell renal cell carcinoma (1); colitis (1); colon cancer (1); colorectal tumor (1); glioblastoma (1); Hyperglycemia (1); infection (1); lung (1); lymphoma (1); major depressive disorder (1); Meckel-Gruber syndromes (1); migraines (1); neuropathy (1); Obesity (1); pancreatic cancer (1); pituitary tumor (1); serous ovarian cancer (1); small cell lung carcinoma (1); Stroke (1); thyroid cancer (1).